FLOT1 (flotillin 1)
Diseases named in the same sentence as FLOT1 in open-access papers (continued):
Sharing a sentence is not in itself a finding about the gene and the disease.
Sepsis (2 papers, 2021). Sepsis is defined as life-threatening organ dysfunction caused by a dysregulated host response to infection. "To determine whether these particles could be EVs produced by the CP, similar to what we described in sepsis, we analyzed the expression of several EV markers, namely ALIX, ANXA2, CD63, FLOT1 and RAB5, in brain samples from early stage AD mice compared to WT age-matched control mice." (PMID 34425919, 2021).
squamous cell carcinoma (2 papers, 2013 to 2014). A carcinoma arising from squamous epithelial cells. "We investigated the mRNA expression of flotillin-1, stomatin, and caveolin-1 using real-time PCR in 22 paired (tumor and corresponding normal tissue) samples of adenocarcinomas and 26 paired samples of squamous cell carcinomas." (PMID 24533441, 2014). "The prognostic and biological significance of ACE2, FLOT1 and especially PRKD1 merits prospective validation, in order for these factors to possibly serve as independent prognostic markers for recurrence in patients with surgically resected squamous-cell carcinoma of the larynx." (PMID 23950933, 2013).
type 2 diabetes (2 papers, 2016 to 2019). "Recently, compared to healthy controls, a more than four-fold increase of the abundance of flotillin-1 (FLOT1) was observed in RBC membranes of humans with type 2 diabetes." (PMID 31195708, 2019). "One of the major integral protein of erythrocyte lipid raft, flotillin-1 was reported to be affected in type 2 diabetes, after human red blood cells membranes were investigated using a proteomic approach by two-dimensional electrophoresis." (PMID 32309579, 2016).
acute appendicitis (1 paper, 2025). "Additionally, through the colocalization analysis, we identified five shared pleiotropic genes between MDD and acute appendicitis: C4A, FLOT1, LINC00243, MICB, and PRSS16." (PMID 41438618, 2025). "Finally, the colocalization analysis identified five shared pleiotropic genes for MDD and acute appendicitis: C4A, FLOT1, LINC00243, MICB, and PRSS16." (PMID 41438618, 2025). "And we found that five genes C4A, FLOT1, LINC00243, MICB, and PRSS16 shared the same tissues between MDD and acute appendicitis." (PMID 41438618, 2025). "Finally, we defined three shared genes: PRSS16, ZNF602P, and ZNF204P by TWAS and nine pleiotropic genes C4A, FLOT1, LINC00243, MICB, and PRSS16 by colocalization analysis between MDD and acute appendicitis." (PMID 41438618, 2025).
acute lymphoblastic leukemia (1 paper, 2025). Leukemia with an acute onset, characterized by the presence of lymphoblasts in the bone marrow and the peripheral blood. "For instance, S100A8/A9 heterodimers have been shown to drive GSDMD-dependent pyroptosis in acute lymphoblastic leukemia (ALL), while FLOT1 promotes AML progression through dual suppression of pyroptosis and apoptosis." (PMID 41267084, 2025).
amyloid (1 paper, 2014). "In brain from flotillin 1-/- and flotillin 1-/-, flotillin 2-/- mice expressing the APPPS1 transgenes we observed less Aβ and less amyloid plaques, as compared with controls." (PMID 24465508, 2014).
asthenozoospermia (1 paper, 2023). "In detail, the combination of the three proteins APCS, APOE, and FLOT1 predicts male subfertility in general, the two combined proteins APOE and FN1 predicts asthenozoospermia, and the two combined proteins RUVBL1 and TFKC oligoasthenozoospermia." (PMID 37048090, 2023).
asthma (1 paper, 2025). "For example, FLOT1 was expressed in all 13 immune cell types, but only the scTWAS GReX model in MonoNC was predictive, and significant associations with RA, SLE and asthma were observed only in this cell type." (PMID 41256005, 2025).
autoimmune conditions (1 paper, 2025). "Cell-based and immunoprecipitation assays found rare MS-specific anti-flotillin-1/2 antibodies in serum, with little to no overlap with other neurological or autoimmune conditions, but their occurrence is infrequent (~2%), and their contribution to pathogenesis is yet unsubstantiated." (PMID 41226806, 2025).
autoimmune disease (1 paper, 2025). A disorder resulting from loss of function or tissue destruction of an organ or multiple organs, arising from humoral or cellular immune responses of the individual to their own tissue constituents. "Since FLOT1 was also implicated as a candidate gene in other autoimmune diseases, including RA and SS, we subsequently assessed its expression in these cohorts." (PMID 40599891, 2025). "Notably, FLOT1 was the only gene found to both share a genetic variant and be identified as a causal gene across the five autoimmune disorders." (PMID 40599891, 2025). "Our Bayesian colocalization analysis revealed five genes, including GTF2H4, FLOT1, HCP5, immediate early response 3 (IER3), and serine/threonine kinase 19 (STK19), that were identified as having a shared variant with autoimmune diseases (PP.H4 > 0.8)." (PMID 40599891, 2025).
benign adenomas (1 paper, 2025). "Compared to the different ovarian tumors from another GEO data set (GSE57477), we found that the levels of FLOT1 mRNA expression were higher in serous ovarian adenocarcinomas (n = 46) and borderline tumors (n = 6) than in benign adenomas (n = 20)." (PMID 40066501, 2025).
Brain tumor (1 paper, 2022). "Brain tumor CSCs express the exosomal markers TSG 101 (tumor susceptibility gene) and flotillin 1 which can suppress T-cell activity by the upregulation of tenascin-C." (PMID 35163368, 2022).
colon adenocarcinoma (1 paper, 2013). "However, in human colon adenocarcinoma HT-29 cells, in which rafts are important for complex formation between p120catenin and E-cadherin, depletion of flotillin-1 leads to a diffuse localization of both proteins and impairs their recruitment in lipid rafts." (PMID 24391950, 2013).
COVID-19 (1 paper, 2022). A disease caused by infection with severe acute respiratory syndrome coronavirus 2. "EVs collected from the serum of both healthy controls and patients with COVID-19 were confirmed by transmission electron microscopy, and western blotting confirmed the expression of CD9, CD63, and flotillin-1, while calnexin and haptoglobin expressions were negative." (PMID 36451245, 2022).
dementia (1 paper, 2022). Loss of intellectual abilities interfering with an individual's social and occupational functions. "However, low brain PL 18:0/22:6 (<mean-1SD) and high levels of tangles and flotillin-1 (>mean+1SD) and intermediate levels of amyloid (mean ± 1SD) predicted dementia." (PMID 36092723, 2022).
ductal carcinoma in situ (1 paper, 2014). "CD44 co-localised extensively with Flotillin-1 in the cell membranes of ductal carcinoma in situ cultures, but there was little spatial overlap of these proteins in invasive ductal carcinoma cultures." (PMID 24512624, 2014).
end stage renal disease (1 paper, 2024). "Using microarray gene expression network analyses, FLOT1 was also identified as a potential target regulated by core transcription factors related to the immunoreaction in nocturnal hemodialysis treatment in end stage renal disease patients." (PMID 38459044, 2024).
endometrial cancer (1 paper, 2024). Primary or metastatic malignant neoplasm involving the endometrium (mucous membrane that lines the endometrial cavity). "FLOT1 behaves as an oncogene in endometrial cancer, leading to growth and tumor invasion by activating regulators like ERK, AKT, and TGF-β." (PMID 38731868, 2024).
fibromyalgia (1 paper, 2014). A chronic disorder of unknown etiology characterized by pain, stiffness, and tenderness in the muscles of neck, shoulders, back, hips, arms, and legs. "Fibromyalgia has been genetically linked to the HLA region (6p21.3) 63, which includes several genes associated with Notch signalling (e.g. Notch4, FKBP5, TNXB, MTCH1 and TNF-a) or with stem cell maintenance and proliferation (e.g. POU5F1, Flot1, MAPK14, Rgl2 and Rab44)." (PMID 25164209, 2014).
head and neck cancer (1 paper, 2013). A primary or metastatic malignant neoplasm affecting the head and neck. "These are novel findings, since none of ACE1, FLOT1 and PRKD1 have previously been investigated in laryngeal or head and neck cancer, neither is it known whether these genes are functional in the normal laryngeal epithelium." (PMID 23950933, 2013).
Hypercholesterolemia (1 paper, 2024). An increased concentration of cholesterol in the blood. "In such case, the identification of A2AR and Flotillin-1 downregulation and transferrin and ferritin alterations might represent a novel panel of very early predictive biomarkers of the cardiovascular risk in hypercholesterolemia." (PMID 38534331, 2024). "The identification of altered Flotillin-1 and A2AR expression in hypercholesterolemia provides new insights into the mechanisms of LDL-C excess toxicity." (PMID 38534331, 2024).
Insulin resistance (1 paper, 2021). Increased resistance towards insulin, that is, diminished effectiveness of insulin in reducing blood glucose levels. "In the present study, the decreased PrPc level and its interaction with flotillin-1 and CAP in TBI mice brains suggests that PrPc plays a potential molecular linking role in brain insulin resistance in TBI." (PMID 34445708, 2021).
laryngeal carcinoma (1 paper, 2013). Carcinoma that arises from the laryngeal epithelium. "It should be noted, however, that the differences observed in the expression of ACE2, FLOT1 and PRKD1 in favourable and unfavourable laryngeal carcinomas were not clear-cut in the array predictor, which may reflect the lack of direct genomic alterations within the corresponding gene sequences." (PMID 23950933, 2013).
lentivirus infection (1 paper, 2023). Virus diseases caused by the Lentivirus genus. "To investigate the effect of FLOT1 on radiation resistance, we prepared FLOT1 knockdown shRNAs and further transfected them to A549/X and H520/X cells by lentivirus infection, then detected the knockdown efficiency by Western blotting." (PMID 37131290, 2023).
liposarcoma (1 paper, 2014). A usually painless malignant tumor that arises from adipose tissue. "We also found differences in mRNA expression of caveolin-1 and flotillin-1 between liposarcomas and other mesenchymal tumors (p < 0, 05, χ2-test)." (PMID 24533441, 2014).
lung squamous cell carcinoma (1 paper, 2024). "For lung squamous cell carcinoma, 9 genes were causally related, comprising U91328.19, FLOT1, LINC00243, HLA-DQA1, HLA-DQB1, HLA-DQB1-AS1, HLA-DQB2, ZNF483 and BLOC1S2." (PMID 38834983, 2024).
membranous nephropathy (1 paper, 2024). "These reported potential immune system involvements of FLOT1 would align with clinical features of membranous nephropathy which is an auto-immune type of kidney disease." (PMID 38459044, 2024).
metastatic prostate carcinoma (1 paper, 2019). A carcinoma that arises from the prostate gland and has spread to other anatomic sites. "The present study identifies that Flot-1 is a novel sumoylation target protein, and sumoylation of Flot-1 positively regulates Snail stability to promote EMT of metastatic prostate cancer." (PMID 30631151, 2019). "The present study shows that palmitoylation is dispensable, but sumoylation is required for mitogen-induced nuclear targeting and interaction with Snail of Flot-1 to function as a positive regulator in Snail-mediated EMT in metastatic prostate cancer." (PMID 30631151, 2019). "Our study reveals a new mechanism of sumoylated Flot-1-mediating Snail stabilization, and identifies a novel sumoylated Flot-1-Snail signaling axis in EMT of metastatic prostate cancer." (PMID 30631151, 2019). "Herein, we show that up-regulated E2 conjugating enzyme UBC9 sumoylates Flot-1 at Lys-51 and Lys-195 with small ubiquitin-like modifier (SUMO)-2/3 modification in metastatic prostate cancer." (PMID 30631151, 2019).
myelitis (1 paper, 2017). An inflammatory process affecting the spinal cord. "In the six anti-flotillin-1/2-positive patients in whom the antibody was found prospectively and for whom we could evaluate medical records, testing for anti-AQP4 and anti-MOG was initially requested based on clinically assessed NMOSD core characteristics like myelitis and/or optic neuritis." (PMID 28645295, 2017).
Neurofibrillary tangles (1 paper, 2022). Pathological protein aggregates formed by hyperphosphorylation of a microtubule-associated protein known as tau, causing it to aggregate in an insoluble form. "The association of high brain polyunsaturated (PUFA)-PL levels with better cognition was independent of amyloid plaque, neurofibrillary tangle, PE, and flotillin-1 expression." (PMID 36092723, 2022).
neuropathy (1 paper, 2019). A disorder affecting the nervous system that manifests with pain, tingling, numbness, and/or muscle weakness. "Notably, FLOT1 and FLOT2 were markedly depleted in RTX neuropathy associated with TRPV1(+) neuronal depletion." (PMID 30578250, 2019).
oral cancer (1 paper, 2019). "We also observed lower flotillin-1 expression in BME treated cells, suggesting BME treatment inhibits lipid rafts in oral cancer cells." (PMID 31638999, 2019).
ovarian benign tumors (1 paper, 2025). "Next, we measured and compared the serum levels of FLOT1 and CA125 between healthy controls, patients with ovarian benign tumors, and patients with OC before and after the operation." (PMID 40066501, 2025).
ovarian tumor (1 paper, 2025). "Knockdown of FLOT1 by FLOT1‐siRNA inhibits the proliferation of OC cells and arrests the cell cycle at the S phase, whereas suppression of FLOT1 increases cyclin E1 protein, indicating that FLOT1 plays an important role in ovarian tumor growth." (PMID 40066501, 2025).
Parkinson disease (1 paper, 2025). A progressive degenerative disorder of the central nervous system characterized by loss of dopamine producing neurons in the substantia nigra and the presence of Lewy bodies in the substantia nigra and locus coeruleus. "Flotillin 1 is highly expressed in the brainstem catecholaminergic neurons and is strongly upregulated in Parkinson's disease." (PMID 39877933, 2025). "According to another mechanism that relies on flotillins but not on their upregulation, Parkinson's disease‐associated DJ‐1/PARK7 deficiency is associated with flotillin 1 decrease and altered glutamate endocytosis that could exploit the role of flotillins as scaffolds of lipid raft domains." (PMID 39877933, 2025).
promyelocytic leukemia (1 paper, 2019). "Expression levels of FLOT1 and FLOT2 during A. phagocytophilum infection in human promyelocytic leukemia (HL-60) and monkey endothelial (RF/6A) cell lines were measured by quantitative reverse transcription-PCR (qRT-PCR) and Western blotting." (PMID 30914515, 2019).
serous ovarian adenocarcinomas (1 paper, 2025). "IHC confirmed the overexpression of FLOT1 protein in OC tissue as shown strong staining in serous ovarian adenocarcinomas was observed, which was consistent with the data from the GEO database." (PMID 40066501, 2025).
transitional cell carcinoma (1 paper, 2017). A malignant neoplasm arising from the transitional epithelium, usually affecting the urinary bladder, ureter, or renal pelvis. "A new study indicated that Flotillin-1 expression was upregulated significantly in transitional cell carcinomas(TCCs) compared to normal urothelial tissue, moreover, Flotillin-1 expression was significantly associated with tumor size, pathologic grade, clinical stage and recurrence based on t-tests." (PMID 28881760, 2017).
tumor (56 papers, 2013 to 2026). "Recent studies have shown the overexpression of flotillin-1 in various types of malignancies and have demonstrated that flotillin is associated with tumor development and metastasis." (PMID 39516745, 2024). "The FLOT1 is highly expressed in prostate tissue and its role reflects the cellular function of cytoskeleton, associated with cell proliferation, cell migration and tumor progression, cell invasion, and treatment resistance." (PMID 39404386, 2024). "FLOT1 upregulation was associated with tumor progression and patient survival." (PMID 26002553, 2015). "Tumor growth was monitored for up to 33 days post IR to assess the combined effect of FLOT1 depletion and IR on tumor growth in vivo." (PMID 40335491, 2025). "Application of a methylation inhibitor, 3‐deazaadenosine, decreased FLOT1 mRNA expression in OC cells and suppressed tumor formation in a xenograft mouse model." (PMID 40066501, 2025). "Inhibiting the m6A modification by 3‐DAA decreased the level of FLOT1 mRNA and suppressed tumor formation." (PMID 40066501, 2025). "Immunohistochemistry (IHC) assays revealed higher levels of INSIG1 expression in Anta‐137463 group (II) compared to g Anta‐NC group (I) whereas the expression of SREBP2, FLOT1, and Ki67 was markedly diminished within the xenograft tumor tissues." (PMID 39692168, 2025). "The prognosis of the FLOT1 HR and FLOT1 LR subgroups was evaluated based on tumor stage (tumor stage I-II vs. tumor stage III-IV)." (PMID 40335491, 2025). "Although previous studies have explored the role of FLOT1 in tumor progression and invasion, its potential involvement in mediating radiation resistance remains unexplored." (PMID 40335491, 2025). "In a xenograft model, the combination of CH siFLOT1 with IR resulted in a significant reduction in tumor growth compared to either treatment alone, reinforcing the efficacy of targeting FLOT1 to enhance the therapeutic response to RT." (PMID 40335491, 2025). "Research on PCa has revealed that sustained SUMOylation of ATF3 can activate the cell cycle and promote tumor proliferation, while SUMOylated flotillin-1 can undergo nuclear translocation to promote epithelial–mesenchymal transition (EMT) transformation." (PMID 39623295, 2024). "miR‐182‐5p indirectly inhibits AKT2 activity by targeting FLOT1, resulting in increased activity of the downstream transcription factor FOXO3a, thereby suppressing tumor cell proliferation." (PMID 39092291, 2024). "The expression levels of FLOT1 and BCAR1 were both significantly associated with tumor stage, depth of tumor invasion and regional lymph node." (PMID 37928269, 2023). "We found that the tumours from FLOT1‐OE group were larger in size and weight than that in control group, which indicated that FLOT1 overexpression dramatically increased GBM xenograft tumour development." (PMID 36647700, 2023). "Results also showed that Ki-67 expression level was higher in FLOT1-OE xenograft tumor and lower in FLOT1-KD group when compared to the corresponding control." (PMID 37928269, 2023). "LncRNA A1BG-AS1 is reported to facilitate BC tumor growth and malignant cell behaviors by binding with miR-485-5p to regulate (flotillin-1) FLOT1 expression." (PMID 38007504, 2023). "Given that FLOT1 was reported to facilitate tumor development by regulating protein stability, FLOT1 was selected, from 29 protein molecules detected by IP-MS, as the subject in this study." (PMID 37131290, 2023). "FLOT1 promotes tumor progression, induces the epithelial-mesenchymal transition and regulates cell cycle in LUAD by regulating the ERK pathway." (PMID 36629518, 2023). "When combined with radiotherapy, the control group exhibited robust efficacy of tumor destruction, contrary to the FLOT1 overexpression group." (PMID 37131290, 2023). "In this study, considerable attention was focused not only on the impact of FLOT1 on tumor cells directly but also on the immune microenvironment that affects the radioresistance in NSCLC." (PMID 37131290, 2023).